FABP4 (fatty acid binding protein 4)
Diseases named in the same sentence as FABP4 in open-access papers (continued):
Sharing a sentence is not in itself a finding about the gene and the disease.
tumor (continued). "From a methodological perspective, single-cell sequencing and spatial transcriptomics can parse the cell-specific expression of FABPs within the tumor microenvironment (e.g., high expression of FABP4/5 in TAMs and fibroblasts)." (PMID 40717587, 2025). "In CRC, FABP4 is a key regulator, contributing to tumour progression, metastasis, metabolic reprogramming, and drug resistance." (PMID 41149452, 2025). "Targeting FABP4 can reshape the tumor immune microenvironment and enhance the efficacy of PD-1 inhibitors." (PMID 40717587, 2025). "Conversely, under high glucose conditions, adipocytes can transfer miRNAs (such as miR-130b) or lipid metabolism-related proteins (such as FABP4) via exosomes, promoting lipid accumulation in other cells (such as myocytes or tumor cells) in the co-culture." (PMID 40244284, 2025). "In this state, endothelial cells exhibit increased lipid uptake and enhanced expression of FABP4, and inhibition of FABP4 can reduce tumor angiogenesis." (PMID 40718481, 2025). "The finding suggests that these intrinsic factors also hinder HCC tumor formation, in addition to the paracrine effects of FABP4." (PMID 41392988, 2025). "Collectively, these observations suggest that FABP4 is potentially a critical biomarker for tumor growth, metastasis, and anti-tumor drug sensitivity of OC." (PMID 40429934, 2025). "Overexpression of FABP4 in HCC cell lines inhibited proliferation and migration in vitro and suppressed tumour growth in vivo, while FABP4 knockdown showed the opposite effect." (PMID 41149452, 2025). "Anti-FABP4 neutralizing mAb suppresses cancer stemness and inhibits tumor growth in a MASLD-HCC mouse model." (PMID 41392988, 2025). "Compared with normal tissues, the top three downregulated genes in the tumor tissues were FABP4, SAA1, and SFRP1, while the top three upregulated genes were COMP, COL10A1, and MMP11." (PMID 40936892, 2025). "FABP4 also promotes pancreatic cancer progression by enhancing tumour cell proliferation and supporting redox homeostasis." (PMID 41149452, 2025). "FABP4 also regulates angiogenic and metabolic signaling in tumor-associated endothelial cells, in which the transcription factor FOXO1 promotes VEGFA-induced FABP4 expression." (PMID 40814339, 2025). "Adipocytes and FABP4 work together extensively to regulate pathological processes such as tumor stromal remodeling and EMT." (PMID 39984452, 2025). "On the other hand, FABP4 and FABP5 have been implicated in HCC tumour progression and patient prognosis as reported by several IHC and tissue microarray studies." (PMID 41154605, 2025). "Key genes, including CD36, FABP4, PLIN1, PLIN4, SCD5, and ACSLs, were consistently downregulated in tumor tissues, with further reductions observed in KRAS-mutated samples." (PMID 40860798, 2025). "FABP4—one of the most critical adipokines—has been shown to be closely upregulated and involved in tumor cell dysfunction and progression." (PMID 41226657, 2025). "To assess the nature of intercellular interactions in SARIFA areas, we analyzed the expression of CD36 and FABP4, genes known to be involved in alterations of fatty acid metabolism at the interface between tumor cells and adipocytes." (PMID 41228384, 2025). "As a lipid metabolism hub molecule, FABP4 plays a central role in cancer progression by regulating the tumor microenvironment, immune evasion, and metabolic adaptation." (PMID 40717587, 2025). "The tumor cells in SARIFAs express FABP4 (Fatty Acid Binding Protein 4) and show a higher expression of CD36, which indicate the capability of the tumor cells for taking up and breaking down fatty acids." (PMID 39335115, 2024). "An alternative pathway of transportation of saturated and unsaturated lipids and fatty acids between tumour cells and adipocytes is conducted through fatty acid binding protein 4 (FABP4)." (PMID 38926671, 2024).
tumor (continued). "Epitope analysis of V9 binding to FABP4 indicated that V9 uniquely bound to β1, β-3/4, and β-7, potentially affecting fatty acid transport, lipid metabolism and signaling in tumor cells." (PMID 39054536, 2024). "Instead, lipid droplets formed by LA in WT macrophages were depleted following coculture with tumor cells, showing the pro-migration effect of FABP4-mediated lipolysis." (PMID 39513934, 2024). "Given that FABP4 has been identified as a strongly upregulated gene with heightened protein expression, along with growing evidence of a tumor-promoting effect of this protein, FABP4 inhibitors, such as BMS309403, are of great interest." (PMID 37874427, 2024). "Given the ample evidence for the major role of lipid metabolism in tumor progression in cancer in general, but also in the context of PCa, we studied the immunohistochemical protein expression of FABP4 and CD36, both key players in fatty-acid metabolism." (PMID 38216952, 2024). "Consistent with our previous observations in FABP4−/− mice, V9 treatment reduced tumor stemness, as evidenced by reduced ALDH1 activity." (PMID 39054536, 2024). "To investigate alterations in tumour metabolism and microenvironment, we performed immunohistochemical staining for FABP4, CD36 and CD68." (PMID 38926671, 2024). "Accordingly, the authors observed an increased tumor growth when FABP4 is overexpressed in macrophages." (PMID 38397187, 2024). "Silencing FABP4 in blood vessels, while preserving its expression in adipose tissue, results in decreased vessel density and tumor growth, underscoring its significant role in tumor angiogenesis." (PMID 38727260, 2024). "Previous studies report that adipocyte-derived FABP4 can act as a paracrine/endocrine signaling entity to promote tumor progression in several different types of cancer arising adjacent to neighboring adipocytes (ovarian, prostate, and breast)." (PMID 38672422, 2024). "FABP4 is highly expressed in adipocytes, and depletion of FABP4 largely inhibits metastatic tumor growth in mice." (PMID 39125923, 2024). "FABP4 facilitates lipid transport and the transfer of free fatty acids to tumor cells, playing a role in the process of tumor bone metastasis." (PMID 38571500, 2024). "It is worth noting that the upregulation of FABP4 is highly influenced by direct interactions between tumor cells and adipocytes." (PMID 39085485, 2024). "SCD1 and fatty acid binding protein 4 (FABP4) contribute to the resistance to ferroptosis during tumor recurrence." (PMID 38575922, 2024). "High lipoprotein-A and visceral fat are key risk factors indicating the expression of FABP4 in CRC patients, where FABP4 promotes tumour angiogenesis." (PMID 38610991, 2024). "At the invasion front of SARIFA-positive PDAC, we observed significantly higher expression of FABP4 (p < 0.0001) and higher concentrations of CD68+ macrophages (p = 0.031) related to a higher risk of tumour progression." (PMID 38926671, 2024). "Once tumor-induced lipolysis occurs, FABP4/unsaturated FAs are secreted from TAMs to induce tumor migration and metastasis." (PMID 39513934, 2024). "In gastric cancer, FABP4 promotes tumour growth by discouraging the survival of tissue-resident memory T cells, as they cannot compete with cancer cells for fatty acid uptake." (PMID 38610991, 2024). "Collectively, these results suggested that blocking FABP4 activity with the S-V9 antibody exerts a profound effect on mitochondrial energy metabolism of tumor cells, potentially contributing to the observed therapeutic outcomes." (PMID 39054536, 2024). "Expression of ANGPTL4, CD36 and FABP4, proteins involved in fatty acid metabolism, was analyzed in marginal tumor cells using an immune reactive score." (PMID 39456610, 2024). "In NB orthotopic and metastatic mouse models with FABP4 KO macrophages the tumor growth is repressed." (PMID 38397187, 2024). "FABP4 transfers the fatty acids from adipocytes to tumor cells and accelerates proliferation and angiogenesis in cancer." (PMID 39220365, 2024).
tumor (continued). "Checking the tissue distribution of each subset revealed multiple tumor-enriched subsets, including all tip cell subsets, E12-capillaries-FABP4, and E16-arteries-COL1A1." (PMID 39345334, 2024). "We also examined the association of other variables, including age, tumor grade, multifocality, lymphovascular invasion, mortality, hormone status, with CD163 and FABP4 expression in tumor tissues." (PMID 39513934, 2024). "Tumour cells in SARIFA-positive cases showed higher expression of FABP4 at the invasion front than in SARIFA-negative cases (p < 0.0001)." (PMID 38926671, 2024). "FABP4 protein expression in the tumour cells and the presence of regional lymph node metastases were inversely associated (χ2= 5.309, p = 0.021)." (PMID 38361045, 2024). "Migration, invasion, and tumor growth are enhanced by increased FABP4 expression through a FABP4-promoted detachment of tumor cells through the extracellular matrix (ECM), for which fatty acid oxidation (FAO) is essential." (PMID 37874427, 2024). "If FABP4 is experimentally downregulated on a genetic or pharmacological level, tumor progression is reduced." (PMID 39085485, 2024). "For example, FABP4 showed high expression in tumour surrounding adipocytes and COL5A2 was expressed in tumour-associated fibroblasts." (PMID 38361045, 2024). "FABP4, a low-molecular-weight protein responsible for transporting long-chain fatty acids and other hydrophobic ligands, has a significant impact on tumor initiation, progression, and treatment." (PMID 39610918, 2024). "In this experiment, the induction of Cd36 and Fabp4 transcription by rosiglitazone was significantly inhibited in both models, suggesting impairment of the Pparg pathway within the stroma of tumor-bearing mammary glands." (PMID 37816052, 2023). "In the largest of the two studies (100 CRC cases), it was also shown that FABP-4 expression was statistically significantly higher in tumor tissues than in adjacent tissues." (PMID 37833736, 2023). "This study confirmed the oncogenic role of FABP4 in liver carcinogenesis, highlighting the key role of tumor microenvironment via cross-talks between endothelial and tumors cells mainly through microvesicles release from endothelial cells." (PMID 37950277, 2023). "In gastric cancer, PD-L1 blockade augments the expression of FABP4/5 and lipid uptake of tissue-resident memory T cells (Trm), thereby extending their lifespan and enhancing their anti-tumor effects." (PMID 37700339, 2023). "Several preclinical studies have demonstrated the efficacy of targeting fatty acid transporters such as fatty acid translocase, CD36, and fatty acid binding protein 4 (FABP4) in reducing tumor growth in various cancer types." (PMID 37233659, 2023). "Previous studies have found that M2 macrophages preferentially upregulate FABP4 expression and play a tumor-promoting role through FABP4-dependent IL-6/STAT3 signaling." (PMID 37545500, 2023). "Wilcoxon signed-rank test was used to analyze the correlation between the FABP4 expression (group by median) and patient age, gender, tumor stage, and TNM stage in TCGA." (PMID 37180113, 2023). "FABP4 promotes the colonization of tumor cells in the lipid-rich TME, and its targeted inhibitor inhibits the adaptation of tumor cells to colonization in the TME." (PMID 37277821, 2023). "This identified multiple genes downregulated in tumour-associated adventitial fibroblasts compared to control counterparts, including IGFBP6, FABP4 and DCN." (PMID 36720863, 2023). "Seven hub genes, REG4, S100A7, CLCA1, FABP4, RETNLB, SFRP2, and WNT10A, were all significantly associated with CC patient prognosis and differentially expressed in normal and tumor tissues." (PMID 36941538, 2023). "This was probably due to FABP4, a mediator of lipid transport in adipocytes and tumor-initiating cells." (PMID 37978381, 2023). "Some studies have shown that fatty acid binding protein 4 (FABP4) can promote tumor growth, so inhibiting FABP4 can be used as a way to treat tumors." (PMID 38264667, 2023).
tumor (continued). "FABP4 increased the synthesis of lipid droplets under hypoxic circumstances, which both promoted tumor migration and protected cancer cells from ferroptosis." (PMID 36317423, 2022). "Compared with normal tissues, the expression of FABP4 in more than 10 tumor tissues was lower (p < 0.05)." (PMID 36532833, 2022). "However, the striking differences in the effect of FABP4 between cell populations suggests that the role of FABP4 in tumor progression may depend on the underlying risk factor in which cell transformation occurs, as well as the underlying pathology in which the tumor progresses." (PMID 36358315, 2022). "The lipid transfer between marrow adipocytes and tumor cells can further fuel the growth and invasiveness of tumor cells at the metastatic sites by upregulating FABP4." (PMID 35899119, 2022). "FABP4, belonging to the fatty acid binding proteins (FABPs) family, has a central role in tumour metastasis and endothelial migration by regulating metabolic and inflammatory pathways." (PMID 36578551, 2022). "A bidirectional interaction between the FABP4 and PPARγ pathways has been identified to potentially drive the aggressive behavior of tumor cells in bone." (PMID 36760798, 2022). "Src inhibition impairs LD formation by activating PPARγ-induced FABP4 expression and elevating reactive oxygen species (ROS) production, suggesting the critical role in Src/PPARγ/FABP4 axis in tumor proliferation." (PMID 35899119, 2022). "FABP4 is mainly expressed in white and brown adipose tissues, macrophages, and monocytes and upregulation of adipocyte-derived FABP4 promotes tumor progression." (PMID 35721518, 2022). "A strong positive FABP4 signal was detected in normal tissues, and a clear decrease in FABP4 signal was observed in tumour tissues." (PMID 35198079, 2022). "FAPB4 is a tumor suppressor, the expression of FABP4 is significantly correlated with tumor stage, disease-free survival (DFS) and overall survival (OS)." (PMID 36264920, 2022). "FABP4 related immunomodulators was identified by Tumor and Immune System Interaction Database (TISIDB) database, and a prognostic risk signature was constructed based on FABP4-related immunomodulators using stepwise Cox regression analysis." (PMID 36264920, 2022). "The following section focuses on the emerging roles of FABP4 during initial cell transformation and consecutive tumor progression." (PMID 36060264, 2022). "Recent studies have found that FABP4 specific inhibitor BMS309403 not only significantly reduces tumor burden in a syngeneic orthotopic mouse model but also increases the sensitivity of cancer cells toward carboplatin." (PMID 35899119, 2022). "Mechanistically, it was suggested that FABP4 pathway bidirectionally interacts with that of PPARγ to drive aggressive tumor behavior in bones." (PMID 35406450, 2022). "By comparing tumor with adjacent tissue, or comparing a metastatic tumor with non-metastatic tumor, we observed that FABP3 and 4 were expressed in a fraction of myeloid cells, and FABP4 displayed a marginal reduction in cells from metastatic tumor tissues." (PMID 35269427, 2022). "Among patients with non-small cell lung cancer, high expression of FABP4 is correlated with advanced tumor node metastasis stage." (PMID 35899119, 2022). "Lipid desaturation of SCD1 in cancer cells and the lipid transport of FABP4 produced by tumor endothelial cells (TECs) promote the survival of cancer cells and the resistance to iron death in the TME." (PMID 35646090, 2022). "This SCD1/FABP4 network provides tumor intrinsic antioxidant and anti-ferroptotic resources for survival and regrowth in a harsh TME." (PMID 35899119, 2022). "Examination of dissected livers revealed a lower number of tumour foci in the FABP4 overexpression group than that in the control group, and FABP4 knockdown resulted in an opposite trend." (PMID 35198079, 2022).
tumor (continued). "FABP4 enhances tumor proliferation through multiple molecular mechanisms, including rewiring metabolic phenotypes, deregulating DNA methylation and upregulating oncogenic signaling pathways." (PMID 35899119, 2022). "Tumor cells outcompete Trm cells for the uptake of fatty acids to induce Trm cell apoptosis, which is reversed by the PD-1 blockade antibody by increasing the fatty acid-binding protein (Fabp) 4/5 in Trm cells and decreasing Fabp4/5 in tumor cells." (PMID 36231064, 2022). "PD-L1 blockade reduced FABP4/5 expression in tumor cells but increased FABP4/5 expression in Trm cells, providing adequate lipid uptake in Trm cells and contributing to antitumor immune response." (PMID 36569893, 2022). "Other contrary to the other genes, FABP4 was reported to be highly expressed in NSCLC and it was associated with tumor node metastasis." (PMID 36067196, 2022). "The transcriptional activity of PPARγ was deactivated by the oncogene, resulting in the induced expression of the lipolytic gene FABP4, which was accompanied by a reduction in lipid droplets and tumor growth." (PMID 36532833, 2022). "We analyzed the RNA expression levels of FABP4 in different tumor and normal tissues using the TCGA and GETx databases." (PMID 36532833, 2022). "For FABP4, seven and two cases in tumor and normal samples, respectively, exhibited stronger staining, whereas nine and 14 cases in tumor and normal samples, respectively, were with low staining intensity." (PMID 35836930, 2022). "Although FABP4 has been found to be upregulated in most tumor types, FABP4 has also found to be downregulated in certain cancer." (PMID 35899119, 2022). "In these metastatic niches, FABP4 regulates the CAA-tumor interplay by mediating the transport of FAs between tumor cells and CAAs." (PMID 35899119, 2022). "As a key modulating factor, FABP4 coordinates cellular lipid transport and response in both tumor and stromal compartments." (PMID 36060264, 2022). "In hepatocellular carcinoma, FABP4 promotes tumor development by upregulating the angiogenesis gene signature." (PMID 35899119, 2022). "In omental metastases, FABP4, a type of lipid chaperones, was detected at the interface between adipocytes and tumor cells." (PMID 35216285, 2022). "A recent study demonstrated that stearoyl‐CoA desaturase‐1 (SCD1) and fatty acid binding protein (FABP4) play roles in tumor recurrence by reducing the sensitivity of cancer cells to ferroptosis." (PMID 36317423, 2022). "FABP4 also promotes tumor progression by indirectly altering angiogenesis, matrix metalloproteinases (MMP) activity, and cytokine production." (PMID 33931964, 2021). "We also observed that FABP4 overexpression accelerated tumor growth and metastases by IHC staining of Ki67 and TWIST, while FABP4 knockdown exerts the opposite effects." (PMID 33931964, 2021). "Our results also indicate that FABP4 in macrophages increases malignant phenotypes of NB cells in vitro and tumor growth in vivo, whereas knockdown of FABP4 in macrophages suppresses NB cell invasive properties." (PMID 33931964, 2021). "We then took advantage of metastatic NB models by injecting with SK‐N‐SH cells to analyze the influence of FABP4‐altered macrophages on tumor metastasis." (PMID 33931964, 2021). "Ectopic expression of FABP4 promotes DU145 PCa cell invasion in vitro, while in vivo FABP4 knockdown (KD) reduces tumor growth and lung mets formation." (PMID 34386430, 2021). "A recent study showed that tumor cells also upregulate FABP4 and FABP5 expression and outcompete tumor reactive CD8 TRM cells for lipid uptake leading to TRM cell death." (PMID 33922441, 2021). "Luciferase intensity indicated that tumor growth was repressed by FABP4 knockdown macrophages transplantation, while increased by FABP4 overexpression macrophages transplantation." (PMID 33931964, 2021). "Multiple logistic regression analysis showed that expression of FABP4 correlated with tumor size and mitotic index." (PMID 34558731, 2021).